CASR (calcium sensing receptor)
Diseases named in the same sentence as CASR in open-access papers (continued):
Sharing a sentence is not in itself a finding about the gene and the disease.
Obesity (continued). "Adipocytes in vitro show elevated CaSR expression when exposed to proinflammatory cytokines or serum from donors with obesity." (PMID 33076271, 2020). "Spermine and other polyamines are less specific CaSR agonists with a potential physiological role in the context of obesity." (PMID 33076271, 2020). "Considering that CaSR mRNA shows consistency with protein expression, we assessed CaSR transcripts in AT from subjects with obesity." (PMID 33076271, 2020). "Further, due to the obesity-induced increase in antral CaSR mRNA expression, the density of CaSR immunopositive cells was also determined." (PMID 32824949, 2020). "Further work is required to determine the role of the CaSR in the sensing of dietary protein, and the utility of exploiting l-Phe and the GI CaSR system in the treatment of obesity and diabetes." (PMID 28792489, 2017). "An additional pathological role for Ca2+, CaSR, proinflammatory cytokines, and obesity has been suggested." (PMID 27679579, 2016). "For a better insight on the role of CaSR in the pathogenesis of obesity, studies should also test the effect of CaSR modulation in different obesity models, such as diet-induced and genetically modified mice." (PMID 27660614, 2016). "The obesity associated cytokines like TNF-α and IL-1β increase adipocyte CaSR expression by releasing NFκB to translocate to the nucleus and activate the CASR gene at κB response elements in its promoters." (PMID 27679579, 2016). "Elevated ADMA levels may contribute to obesity via multiple mechanisms, such as interfering with insulin signal transduction and glucose metabolism, activating CaSR to promote lipid accumulation, and disrupting hepatic lipid metabolism." (PMID 41235334, 2025). "Furthermore, aberrant high expression of CASR is observed in inflammation, vascular calcification, atherosclerosis, myocardial infarction, hypertension and obesity, and the Xiphophorus ortholog of CASR is overexpressed in the X. maculatus/X. hellerii hybrid." (PMID 38299666, 2024). "CaSR activity can be modulated by ligands and chemoregulators involved in inflammation and cardiovascular disease processes, including hypertension, vascular calcification, atherosclerosis, myocardial infarction, and obesity." (PMID 38715976, 2024). "The expression of the CaSR and autophagy markers were found to correlate with the percentage of body fat, thus implying a tight bond between the CaSR and autophagy in the pathophysiology of obesity." (PMID 36467702, 2022). "Mechanistically, increased [Ca2+]ex in the vicinity of activated or dying cells, possibly due to chronic inflammation, in AT in obesity could contribute to increased CaSR signalling." (PMID 35931812, 2022). "We propose, that [Ca2+]ex-induced, CaSR mediated NLRP3 activation of macrophages in obesity is a relevant trigger of local and systemic inflammation, which might be targeted therapeutically." (PMID 35931812, 2022). "Obesity is also characterized by the infiltration of immune cells within the adipose tissue, which further contributes to adipose inflammation and lipid dysfunction, where the CaSR seems to be a key player in these processes." (PMID 36467702, 2022). "We hypothesised, that this mechanism might contribute to the activation of adipose tissue (AT) in obesity, and investigated [Ca2+]ex-induced, CaSR mediated IL-1β release by macrophages in obesity." (PMID 35931812, 2022). "The aim of the study was, therefore, to investigate the response of monocyte-derived macrophages and adipose tissue samples from people with obesity to increases in [Ca2+]ex in order to test the possible contribution of CaSR to local and systemic inflammation in obesity." (PMID 35931812, 2022). "CaSR is also relevant in pathophysiological processes of white adipose tissue in obesity." (PMID 36685206, 2022). "However, the CaSR has been shown to promote adipose inflammation, thereby altering lipid metabolism and possibly contributing to obesity." (PMID 36467702, 2022).
Obesity (continued). "Our data suggests that agonists of CaSR may be an important target in obesity, as there is conservation of the cellular pathways which may be targeted for L-cell activation." (PMID 33924402, 2021). "Activating CaSR in macrophages, which are prominent in adipose tissues, induces inflammation in preadipocytes via the NLRP3 inflammasome pathway suggesting that interfering with the expression of CaSR in obesity could work as a therapeutic mechanism." (PMID 33804544, 2021). "The anorectic effects of L-Phe are mediated via the CaSR and suggest that L-Phe and the CaSR system in the GI tract may have therapeutic utility in treating obesity and diabetes." (PMID 34943862, 2021). "Future studies are needed to elucidate whether CaSR expression on other adipose tissue related cells or in other disease conditions like obesity play a role in adipose tissue inflammation in-vivo." (PMID 34001955, 2021). "Recent studies have demonstrated that CaSR influences a wide variety of cells and processes that are involved in inflammation, the cardiovascular system, such as vascular calcification, atherosclerosis, myocardial infarction, hypertension, and obesity." (PMID 33804544, 2021). "Therefore, it is possible that a more extreme condition, like obesity, is needed to distinctively elucidate the role of CaSR on adipose tissue inflammation." (PMID 34001955, 2021). "Our aim is to understand the role of CaSR on autophagy in AT from humans with obesity." (PMID 33076271, 2020). "Circulating ghrelin levels are reduced in obesity and, therefore, it is possible that the increase in antral CaSR mRNA in HFD-induced obesity may impact acyl ghrelin secretion." (PMID 32824949, 2020). "In conclusion, HFD-induced obesity increased CaSR mRNA expression in mouse antrum." (PMID 32824949, 2020). "Our data provide evidence that the anorectic effects of l-Phe are mediated via the CaSR, and suggest that l-Phe and the CaSR system in the GI tract may have therapeutic utility in the treatment of obesity and diabetes." (PMID 28792489, 2017). "In this sense, inhibition of CaSR activity in the WAT of obese patients may represent a novel therapeutic approach in this obesity epidemic era." (PMID 27660614, 2016). "Our findings reveal the importance of TRP channels and the CaSR in the sensing of oligopeptides by L-cells and could be exploited as a therapeutic target in the treatment of obesity and type 2 diabetes." (PMID 26215048, 2016). "We propose that CaSR may be one relevant therapeutic target in the struggle to confront the health consequences of the current worldwide obesity pandemic." (PMID 27660614, 2016). "Similarly, CaSR over-expression on peripheral blood monocytes or MDM in obesity could lead to increased G protein-coupled receptor (GPCR) signalling and explain the observed increase of [Ca2+]ex-induced IL-1β release." (PMID 35931812, 2022). "It has been observed that the activation of CaSR in human preadipocytes stimulates autophagy, which is an essential mechanism for cellular homeostasis, because when damaged organelles are not degraded by lysosomes this leads to cardiometabolic comorbidities especially in conditions of obesity." (PMID 33804544, 2021). "Therefore, whether the protein level of CaSR is altered in HFD-induced obesity and responsible for the reduction in ghrelin secretion in obesity requires further investigation." (PMID 32824949, 2020). "Therefore, future studies should also focus on the effects of calcimimetics on adipose tissue inflammation, by treating animals with pharmacological CaSR agonists in different disease conditions like obesity or chronic kidney disease, which could have important clinical implications." (PMID 34001955, 2021). "Thus, the role of CaSR in obesity may relate to both autophagy and inflammation." (PMID 33076271, 2020). "The present review describes the evidence and perspectives of the role of CaSR in WAT and obesity, as a new player in this complex and multifactorial disorder." (PMID 27660614, 2016).
Obesity (continued). "Due to CaSR's unique ability to sense, and thus potentially integrate a variety of signals through distinct allosteric sites, it may be considered a sensor of the local metabolic environment, which is of great interest in complex tissues, or pathogenic contexts such as dysfunctional WAT and obesity." (PMID 27660614, 2016). "This is interesting, considering that AT explants from people with obesity represent a non-naive model comprising inflammation, fibrosis and oxidative stress, and suggests that CaSR’s effect occurs regardless of the pathophysiological state." (PMID 33076271, 2020). "Taken together, the described findings suggest that even though CaSR stimulates WAT proliferation and differentiation, it induces alterations in lipid handling that might contribute to the deleterious effects of obesity." (PMID 27660614, 2016). "As calcium mobilization and calcium-sensing receptor (CaSR)-induced secretion of cytokines like TNF-α is increased in T cells from inflammatory disease such as sepsis, we propose that these pathways link obesity and inflammation to the development of PE." (PMID 26569331, 2015). "However, no data on CaSR mediated NLRP3 inflammasome activation of macrophages in obesity has been published." (PMID 35931812, 2022). "Our data shows that obesity (BMI > 25) does not alter the expression of CaSR on EEC types." (PMID 33924402, 2021). "Therefore, the characteristic reduction in ghrelin secretion in obesity is not due to changes in the number of CaSR immunopositive cells and/or the degree of co-expression of ghrelin and CaSR." (PMID 32824949, 2020). "Looking at all the studies focusing on the roles of CaSR in adipose tissue and obesity, it could be inferred that CaSR does not contribute towards protection of the adipose tissue, but it rather promotes a dysfunctional state and could thereby contribute to CVDs." (PMID 33804544, 2021).
colorectal cancer (23 papers, 2008 to 2025). A primary or metastatic malignant neoplasm that affects the colon or rectum. "We have previously reported that CaSR expression is down-regulated in colorectal cancer (CRC) and that loss of CaSR provides growth advantage to transformed cells." (PMID 25879211, 2015). "Since the methylation level correlated inversely with CaSR mRNA expression, we assume that one of the causes of CaSR loss in colorectal cancer is DNA hypermethylation." (PMID 24691920, 2014). "The loss of CaSR expression in colorectal cancer has been reported previously, however, the causes of this downregulation are not well understood." (PMID 24691920, 2014). "The current study aimed to assess the effect of dietary calcium intake and possible interactions with calcium-sensing receptor (CASR) gene polymorphisms on colorectal cancer risk." (PMID 23555732, 2013). "Then, we evaluated possible gene-environment interactions between CASR polymorphisms and daily calcium intake in the context of colorectal cancer risk." (PMID 23555732, 2013). "In conclusion, we demonstrated that there is an increased risk of colorectal cancer in subjects with low calcium intake and CASR polymorphisms." (PMID 23555732, 2013). "A recent analysis conducted on 1.235 subjects (420 with CRC and 815 controls) investigated the dietary calcium intake and its possible interactions with calcium-sensing receptor (CASR) gene polymorphisms on colorectal cancer risk." (PMID 24267792, 2013). "Our results are generally consistent with those null associations; however, we noticed a meaningful increase in colorectal cancer risk in the low calcium intake group compared to the high calcium group after stratification by CASR risk genotype." (PMID 23555732, 2013). "To date, no major studies have demonstrated interaction effects between calcium intake and CASR polymorphisms on colorectal cancer." (PMID 23555732, 2013). "In this study, we aimed to explore the effects of CASR polymorphisms and calcium intake on colorectal cancer." (PMID 23555732, 2013). "This case-control study aimed to explore the associations between CASR variants with daily calcium intake and colorectal cancer risk in Korea." (PMID 23555732, 2013). "Further investigations will be required to explain the genetic and gene-environmental effects on colorectal cancer in larger sample sizes and using additional CASR functional regions or variants." (PMID 23555732, 2013). "However, in colorectal cancer (CRC) the expression of the CaSR is silenced and the underlying mechanisms leading to its loss are poorly understood." (PMID 24691920, 2014). "However, among patients with the same CASR genotypes, subjects with lower calcium intake showed higher colorectal cancer risk than did subjects with higher calcium intake." (PMID 23555732, 2013). "The associations between CASR polymorphisms and colorectal cancer risk by cancer site." (PMID 23555732, 2013). "The associations between CASR polymorphisms and colorectal cancer risk." (PMID 23555732, 2013). "However, all 4 of the polymorphisms within the CASR showed significantly higher odds ratios for association with colorectal cancer risk in the low-calcium-intake group compared to the high-calcium-intake group." (PMID 23555732, 2013). "CASR has been implicated in mediating the anticarcinogenic effects of calcium on colorectal cancer." (PMID 23555732, 2013). "CaSR A986S polymorphism causing impaired sensing of extracellular calcium might contribute to the development of colorectal cancer." (PMID 18980667, 2008). "Consequently, a deficiency of CaSR is evident in colorectal cancer." (PMID 38920679, 2024). "Though further study is required to fully understand how dietary calcium and CASR interact to modulate colorectal cancer carcinogenesis, our observations suggest that individuals who have low dietary calcium intake should be aware of their colorectal cancer risk and prevention strategies." (PMID 23555732, 2013).
colorectal cancer (continued). "However, all 4 of the CASR polymorphisms investigated showed significant odds ratios for association with colorectal cancer risk in the low calcium intake group compared with the high calcium intake group after adjusting for age, sex, smoking status, alcohol drinking, and monthly household income." (PMID 23555732, 2013). "CASR exerted complicated functions in prostate, breast and colorectal cancer by regulating calcium homeostasis and inflammation." (PMID 38509759, 2024). "We have previously found that CaSR activation with a calcimimetic worsened clinical symptoms in a mouse model of colitis, and upregulated various inflammatory pathways in CaSR-transfected human colorectal cancer cells." (PMID 37153788, 2023). "Extracellular calcium is known to have tumor preventing effects in colorectal cancer and these effects are mediated by the CaSR." (PMID 25879211, 2015). "In this study, we investigated which epigenetic mechanisms would control CaSR expression in colorectal cancer." (PMID 24691920, 2014). "We included only 4 SNPs within the CASR in our investigation of the gene-only and gene-environment interaction effects on colorectal cancer." (PMID 23555732, 2013). "Colorectal cancer: The CaSR is expressed in normal human colonic epithelium, mainly in the upper half of the crypt, and is absent from the crypt base." (PMID 23340319, 2013). "Recently, the effects of the calcium-sensing receptor (CASR) gene on colorectal cancer have also garnered attention." (PMID 23555732, 2013). "A decrease in IL22 following NPS 2143 treatment (together with the reduction in COX2 expression) could thus indicate that CaSR inhibition may indirectly be protective against colorectal cancer development." (PMID 39770982, 2024). "Conditional knockout of CaSR in mouse intestinal epithelium also resulted in several defects, including immunity that was skewed towards a pro-inflammatory response, consistent with the tumor suppressor role of the receptor in colorectal cancer." (PMID 34357109, 2021). "Indeed, restoration of CaSR expression or function inhibited proliferation of colorectal cancer cells." (PMID 28161520, 2017). "We examined the main effects of the CASR on colorectal cancer by sex and cancer sites." (PMID 23555732, 2013). "The results of the current study showed that CASR polymorphisms themselves were not likely to be correlated with colorectal cancer." (PMID 23555732, 2013). "Moreover, in colorectal cancer, CaSR expression is reduced and may have a preventative role in colorectal cancer development based on its role in the anti-inflammatory processes." (PMID 38276259, 2023). "Moreover, they speculated about how the CaSR could be a possible drug target using existing calcimimetics for the treatment of intestinal disorders, such as colorectal cancer and inflammatory bowel diseases (IBDs)." (PMID 36467702, 2022). "Thus, strategies aiming to upregulate CaSR expression may be of value either in prevention and/or treatment of colorectal cancer." (PMID 24691920, 2014). "Our data show that hypermethylation of the CaSR promoter and H3K9 deacetylation, but not H3K4me2 demethylation are important factors that cause silencing of the CaSR in colorectal cancer." (PMID 24691920, 2014). "Therefore, in the present study, we studied the entire CGI located in the second promoter of CaSR and investigated whether DNA hypermethylation and histone modifications, particularly acetylation and methylation of lysines on H3, play a role in silencing the CaSR in colorectal cancer." (PMID 24691920, 2014). "Polymorphisms in the calcium sensing receptor gene and RXRA have been associated with colorectal cancer risk, but to our knowledge no previous studies have evaluated these genes in relation to pancreas cancer risk." (PMID 23826131, 2013).
colorectal cancer (continued). "The results from this study demonstrate that the CaSR inhibits epithelial-to-mesenchymal transition and the acquisition of a stem cell-like phenotype in the colon of mice lacking the CaSR as well as colorectal cancer cells, identifying the CaSR as a key molecule in preventing tumor progression." (PMID 25879211, 2015).